MMP26 (matrix metallopeptidase 26)
Diseases named in the same sentence as MMP26 in open-access papers (continued):
Sharing a sentence is not in itself a finding about the gene and the disease.
tumor (19 papers, 2009 to 2025). "MMP26 has been associated with tumor development, invasion and metastasis of NSCLC but its methylation profile was not reported, our analysis showed it to be highly hypomethylated in Stage II." (PMID 24369052, 2013). "In addition, the authors indicated that MMP-26 is probably involved in the destruction of necrotic tissue of oxygen-deficient tumours and may participate in neovascularisation and angiogenesis." (PMID 33916127, 2021). "As part of this, MMP-26 interacts in tissue remodeling, angiogenesis, and tumor progression, particularly in tumor invasion." (PMID 41281748, 2025). "Studies have shown that MMP-26 is involved in growth, invasion, and angiogenesis within the tumour, thereby contributing to tumour growth and progression." (PMID 40565125, 2025). "MMP-26 immunostaining intensity increased with tumor stage, with invading tumor cells showing the strongest reaction." (PMID 41007705, 2025). "The paired sample comparison graph demonstrated that the expression levels of ILF3, MMP9, MMP10, MMP11, and MMP26 in PCa tumor tissue were elevated than adjacent non-tumor tissues (P < 0.05)." (PMID 40607407, 2025). "In this team’s work, women with benign lesions also had the highest levels of MMP-26 compared to the other patient groups." (PMID 40565125, 2025). "In contrast, MMP26 expression was significantly downregulated in metastases compared to primary tumor tissues." (PMID 40122809, 2025). "The AC2 cluster was characterised by an overexpression of genes like MMP26, ZNF98 and SP100 associated with tumour promotion." (PMID 39167619, 2024). "Unlike several other MMPs that are involved in varied stages of tumor invasion, MMP-26 plays an essential role in the initial stages of skin cancer." (PMID 27271600, 2016). "Here, expression of MMP-26 protein was predominantly located in pre- and early-invasive areas suggesting MMP-26 expression as an early event in promoting GM-CSF dependent tumor invasion." (PMID 23634280, 2013). "FOXF2 and MMP26 were primarily related to tumour metastasis and invasion." (PMID 34645493, 2021). "Therefore, the aim of the present study was to determine plasma levels of MMP-7 and MMP-26 in comparison to the commonly accepted tumour marker (CA 15-3) in various stages of BC." (PMID 33916127, 2021). "MMP-26 may be activated in HCC Huh7 cells when stimulated by fibroblast growth factors that increase tumor proliferation and migration, with the involvement of the extracellular signal-regulated kinase (ERK) and NF-κB pathways." (PMID 31886121, 2019). "Also, tumor formation in distal organs was detected in mice that received MMP-26+CXCR4+HepG2 HCC cells, suggesting that MMP-26 plays a role in the EMT of HCC." (PMID 31886121, 2019). "MMP-9, the most important MMP in SCC tumor growth, is stimulated by MMP-26." (PMID 27271600, 2016). "Moreover, while MMP-26 has been described in vivo in different tumor entities by others 42, 46, 47, we showed – to our knowledge – for the first time an enhanced MMP-26 expression upon GM-CSF overexpression in vivo and in a complex 3D in vitro model." (PMID 23634280, 2013). "We could see that about half MMPs are highly expressed in tumor tissues as compared with normal tissues, including MMP9, MMP10, MMP11, MMP12, MMP15, MMP25, MMP26 (all, P<0.05), while some other MMPs decreased in tumor tissues, including MMP2, MMP14, MMP16, MMP24, MMP28(all, P<0.05)." (PMID 32669958, 2020). "In this work, we present a continuation of the evaluation of matrilysins (MMP-7 and MMP-26) and stromelysins (MMP-3 and MMP-10) as novel tumor markers for women’s diseases —this time, as screening biomarkers of EC." (PMID 40332487, 2025). "The number and length of blood vessels produced as a result of induction by cells expressing MMP-26 was higher than those induced by tumour cells not expressing MMP-26." (PMID 33916127, 2021).
tumor (continued). "Thus, our in vivo data further confirm a functional contribution of GM-CSF overexpression to tumor invasion and malignancy, together with the upregulation of collagenolytic and gelatinolytic activities by enhanced expression of MMP-2, MMP-9, and MMP-26." (PMID 23634280, 2013).
cancer (16 papers, 2010 to 2026). A tumor composed of atypical neoplastic, often pleomorphic cells that invade other tissues. "There are at least 23 matrix metalloproteinases expressed in humans, and MMP21 and MMP26 have been reported to play an important role in the progression of several cancers, including PCa." (PMID 38240702, 2024). "MMP26 may promote cancer invasion and metastasis by activating proMMP-9 by cleaving the proenzyme site of Ala93-Met94 and interacting with TIMP4 to promote cancer progression." (PMID 35954348, 2022). "In addition, MMP26 plays an important role in invasion and metastasis of cancer cells." (PMID 27143441, 2016). "MMP-26 also belongs to the matrilysin group and, like MMP-7, is an important enzyme in the progression of cancer." (PMID 40565125, 2025). "MMPs of the matrilysin (MMP-7 and MMP-26) and stromelysin (MMP-3 and MMP-10) groups also play an essential role in cancer pathogenesis." (PMID 40332487, 2025). "In A549 LC cells, fibroblast growth factor 1 (FGF1) -induced p-FGFR1 activated MMP26, which hence lead to cancer invasion, besides, inhibition of JNK significantly decreased the activation of MMP26 in response to FGF1 stimulation." (PMID 37766868, 2023). "ZKSCAN3 enhances the expression of a variety of target genes involved in cancer cell proliferation (cyclin D2), growth (IGF-2, integrin β4), metastasis (MMP26), and angiogenesis (VEGF)." (PMID 36012568, 2022). "Some MMPs had very high numbers of transcripts present (gene cluster A), while six MMPs in gene cluster C (MMP27, MMP21, MMP20, MMP26, MMP23A, and MMP8) featured scant numbers of transcript copies across any cancer tissue." (PMID 31200666, 2019). "For example, cancer cells and placental cytotrophoblasts secrete pro-GDF-15 dimers which remain anchored to the ECM until the pro-domain is cleaved by the matrix metalloproteinase 26 (MMP26) and PCSKs, respectively." (PMID 41590509, 2026). "We observed statistically significant diagnostic power for MMP-3, MMP-7, and MMP-26 for stage I and II EC patients, rather than AUC = 0.5, and CA125 only for stage II cancer patients." (PMID 40332487, 2025). "However, the role of circulating levels of MMP-7 and MMP-26 in cancer progression and development has still not been elucidated." (PMID 33916127, 2021). "Besides its extensive distribution in cancer cells of epithelial origin, MMP-26 is also restricted in human placenta and uterus, but nor in other normal tissues." (PMID 20074375, 2010). "Proteases present in malignant tumours but not in normal skin included: PGC, BAP1, caspase-8, F13A1, MMP11, MMP23, MMP25, MMP26 and granzyme-A." (PMID 35327667, 2022).
epithelial neoplasm (1 paper, 2005). A benign or malignant neoplasm that arises from and is composed of epithelial cells. "MMP26 has only recently been implicated in tumorigenesis compared to some of the earlier discovered MMPs, and its expression has been found to be elevated in various epithelial neoplasms." (PMID 15928670, 2005).
skeletal disease (1 paper, 2024). "We are now the first research team to determine the plasma concentrations of MMP-26 not only in OSD, but also in any skeletal disease." (PMID 39407715, 2024).
MMP26 also shares sentences with these, for which no sentence is quoted: pancreatic cancer (2 papers); adenomyosis (1); breast tumor (1); cardiovascular disease (1); cervical dysplasia (1); colorectal cancer (1); ductal carcinoma (1); endothelial dysfunction (1); esophageal carcinoma (1); esophagus squamous cell carcinomas (1); glioblastoma (1); gynecological cancers (1); myoma (1); nevoid basal cell carcinoma syndrome (1); ovarian endometrioid carcinoma (1); ovarian tumour (1); polycystic ovary syndrome (1); prostatic intraepithelial neoplasia (1); renal cell carcinoma (1); Sepsis (1); serous cystadenoma (1).